ZNF829 (zinc finger protein 829)
Description:
May be involved in transcriptional regulation.
Synonyms: DKFZp779O175
Tractability: PROTAC: ubiquitination databases record sites on it.
Gene: Protein-coding gene on chromosome 19 (36,888,124 to 36,916,291, reverse strand). Ensembl gene ENSG00000185869.
Subcellular location: Nucleus
Subcellular location (Human Protein Atlas): Nucleoplasm; Nuclear bodies
Gene Ontology:
Molecular function: DNA-binding transcription factor activity, RNA polymerase II-specific; RNA polymerase II cis-regulatory region sequence-specific DNA binding
Biological process: regulation of transcription by RNA polymerase II; regulation of DNA-templated transcription
Cellular component: nucleus
Genetic constraint (gnomAD): Loss-of-function variants: 30 observed, 44.67 expected, observed/expected ratio (o/e) 0.67, 90% interval 0.5 to 0.91. The upper end of that interval is the gene's LOEUF score, 0.91, which puts it in group 3 of 6, group 1 being the genes least tolerant of losing a copy. Missense variants: 417 observed, 539.94 expected, observed/expected ratio (o/e) 0.77, 90% interval 0.71 to 0.84. Synonymous variants: 136 observed, 168.16 expected, observed/expected ratio (o/e) 0.81, 90% interval 0.7 to 0.93.
Homologues: Orthologues: chimpanzee ZNF829 (99% identical), macaque ZNF829 (95% identical), dog ZNF829 (90% identical), pig ZNF829 (85% identical). Paralogues in human: ZNF383 (74% identical), ZNF790 (56% identical), ZNF546 (54% identical), ZNF30 (51% identical), ZNF780B (51% identical), ZNF780A (51% identical), ZFP30 (50% identical), ZNF540 (50% identical), ZNF461 (50% identical), ZFP82 (50% identical), ZNF573 (49% identical), ZFP14 (49% identical), and 164 more.
Diseases named in the same sentence as ZNF829 in open-access papers:
ZNF829 is named in the same sentence as 1 disease in open-access papers, as found by Europe PMC text mining. Sharing a sentence is not in itself a finding about the gene and the disease. The quoted sentences say what the papers report.
colorectal cancer (1 paper, 2019). A primary or metastatic malignant neoplasm that affects the colon or rectum. "ZNF829 hypermethylation is associated with colorectal cancer." (PMID 31796082, 2019).